SNORD1A (small nucleolar RNA, C/D box 1A)
Synonyms: R38A; snR38A
Gene: Small nucleolar RNA gene on chromosome 17 (76,561,634 to 76,561,705, forward strand). Ensembl gene ENSG00000278261.
Gene Ontology:
Biological process: RNA processing
Cellular component: nucleolus
Homologues: Orthologues: chimpanzee SNORD1A (100% identical), macaque SNORD1A (99% identical), mouse Snord1a (83% identical), guinea pig SNORD1A (76% identical). Paralogues in human: SNORD1C (62% identical), SNORD1B (58% identical).
Diseases named in the same sentence as SNORD1A in open-access papers:
SNORD1A is named in the same sentence as 4 diseases in open-access papers, as found by Europe PMC text mining. Sharing a sentence is not in itself a finding about the gene and the disease. The quoted sentences say what the papers report.
cancer (1 paper, 2023). A tumor composed of atypical neoplastic, often pleomorphic cells that invade other tissues. "Current studies have reported that SNORD1A is a survival‐related snoRNA in various carcinomas by analyzing snoRNA cancer genomic data from TCGA database." (PMID 36812125, 2023).
SNORD1A also shares sentences with these, for which no sentence is quoted: Huntington disease (1 paper); leukemia (1); Parkinson disease (1).